CD4 (CD4 molecule)
Diseases named in the same sentence as CD4 in open-access papers (continued):
Sharing a sentence is not in itself a finding about the gene and the disease.
dry eye (continued). "Topical administration of MSCs has been shown to significantly decrease CD4, IL-1, IL-6, and tumor necrosis factor-alpha (TNF-α) levels in dogs affected by keratoconjunctivitis sicca." (PMID 36290184, 2022). "The data presented in this article shows the longitudinal analysis of tear fluid cytokine profiles, blood CD4 and CD8 counts and HIV viral load in 34 dry eye patients with HIV infection during the HAART therapy." (PMID 28224132, 2017). "The purpose of this study was to evaluate the response to desiccating stress (DS), an experimental model of dry eye, in dominant-negative TGF-β type II receptor (CD4-DNTGFβRII) mice." (PMID 22194977, 2011). "NS CD4-DNTGFβRII at 14 weeks of age mice exhibited a spontaneous dry eye phenotype; however, DS improved their corneal barrier function and corneal surface irregularity, increased their number of PAS+ GC, and lowered CD4+ T cell infiltration in conjunctiva." (PMID 22194977, 2011). "The frequency of CD4[+]IL‐17[+] T cells in the cornea, conjunctiva, and lymph nodes was significantly lower than that in the dry eye mouse model in all treatment groups (p < 0.0001)." (PMID 39985258, 2025). "IL-17 was detected in CD4+ T cells by flow cytometry in previous studies using the DS dry eye model, but most did not evaluate IL-17 production by conjunctival γδ T cells." (PMID 35402439, 2022). "The proportion of peripheral CD4 T cells declined by 2- to 3-fold, and the cell number declined by 6- to 7-fold, but the KO mice were absent of dry-eye and scurfy-skin symptoms." (PMID 35210408, 2022). "In addition, the higher CD4/CD8 ratio and the increased percentages of CD14+ (monocytes/macrophages) observed in dry eye patients could be due to the effect of the conjunctival release of pro-inflammatory cytokines and chemokines." (PMID 29673232, 2018). "Autoimmunity in this model has been demonstrated because adoptive transfer of CD4+T cells primed in vivo in mice subjected to DS were capable of inducing dry eye-changes in the cornea and conjunctiva of immunodeficient recipient mice who were never exposed to dry eye conditions." (PMID 22194977, 2011). "In addition, in the BAC induced dry eye murine model, some signs of dry eye disease, such as decreased tear production, low goblet cell density, and pro-inflammatory cytokine induction were observed, but have not yet been validated for CD4 + T cell or IL-2 introduction." (PMID 31738791, 2019). "SS dry eye and non-SS dry eye human-delivered FMT transplanted into germ-free C57BL/6J female mice resulted in decreased corneal barrier integrity and decreased concentrations of CD45+ CD4+ FOXP3+ in cervical lymph node cells, indicating that Treg cells could modulate gut microbiome or vice versa." (PMID 36142642, 2022).
glomerulonephritis (39 papers, 2009 to 2025). A renal disorder characterized by damage in the glomeruli. "CD4+ T cells that recognize specific antigens deposited in the glomerular mesangium cause glomerulonephritis-like kidney injury." (PMID 31317046, 2019). "Evidence indicates that glomerular injury mediated by effector CD4+ T cells in glomerulonephritis involves multiple steps, beginning with loss of tolerance to nephritogenic autoantigens in secondary lymphoid organs." (PMID 29467472, 2018). "However, Mir223 deficiency exacerbated glomerulonephritis in B6-Mir223−−-Faslpr/lpr mice by facilitating the infiltration of S1PR1+CD4+ T cells into kidney tissues." (PMID 33574820, 2020). "IgA nephropathy (IgAN) is the most common primary glomerulonephritis, characterized by glomerular deposition of IgA immune complexes, mainly produced by B cells under the regulation of CD4+T cells." (PMID 35983053, 2022). "While CD4+ T cells dominate in number compared with CD8+ T cells in murine glomerulonephritis models, nearly equal numbers of CD4+ and CD8+ T cells in humans are reported in many studies." (PMID 35411437, 2022). "Since the number of IFN-γ-producing CD4+ T cells was increased to a similar degree, these results indicate that the number of Th1 cells is increased in glomerulonephritis progression in MRL-FaslprKSRP−/− mice." (PMID 34831390, 2021). "Compared to controls and other forms of glomerulonephritis, the percentage of IL-4+CD4+ and IL-10+CD4+ cells are significantly increased (the former is positively correlated with proteinuria), and the Th1/Th2 ratio is significantly lower in PMN patients." (PMID 32973748, 2020). "The following paragraphs will summarize our current knowledge of CD4+ T cell plasticity with a particular focus on glomerulonephritis." (PMID 27974866, 2016). "CD4+CD25-Foxp3+ T cells were also detected in urine sediment samples of patients with active glomerulonephritis and correlated with the extent of proteinuria." (PMID 24774748, 2014). "In patients with active glomerulonephritis, CD4+CD25-Foxp3+ T cells were analyzed in urine sediment samples." (PMID 24774748, 2014). "Adoptive transfer of expanded CD4+CD25+ Tregs inhibited the onset of glomerulonephritis and prolonged survival in mice." (PMID 19551149, 2009). "Compared to mice immunized with cured heat-killed S. aureus JH1, mice immunized with S. aureus JH1 containing pSJH101 developed glomerulonephritis with pathological albuminuria, glomerular focal, and segmental necrosis and infiltrates of CD4+ T cells, CD8+ T cells and macrophages." (PMID 31358739, 2019). "The CD4+RORγt+FoxP3+ T cells represented intermediates during Tregs/Th17 transdifferentiation, and constituted an independent biofunctional regulatory cell lineage which contributed to cresecentic glomerulonephritis." (PMID 30992023, 2019). "Therefore, the aim of this study is to investigate the mechanisms of intravascular antigen presentation to disease-initiating, antigen-experienced effector CD4+ T cells in the glomerulus, using a validated model of T-cell-mediated glomerulonephritis." (PMID 29467472, 2018). "In addition to humoral mediators, CD4+ T cells also have an important function in the development of glomerular injury and dysfunction in severe, rapidly progressive forms of glomerulonephritis." (PMID 29467472, 2018). "Multiple studies have identified CD4+ T cells as central players of glomerulonephritis (GN)." (PMID 27974866, 2016). "However, studies on the pathogenesis of glomerulonephritis of other aetiologies have revealed the involvement of T cells and adhesion molecules, and in a previous study, we detected CD4+ T cells in the glomeruli in small sample of five dogs with naturally acquired VL from an endemic area." (PMID 20459816, 2010). "This study investigates the therapeutic potential of blocking key CD4+ Th1 effector cytokines, TNF-α and IFN-γ, in experimental anti-myeloperoxidase (MPO) glomerulonephritis (GN)." (PMID 40735321, 2025).
glomerulonephritis (continued). "Recent studies on mouse models of glomerulonephritis also showed that AREG can enhance the function of Treg cells, inhibit the growth of CD4+ T cells, and promote the recruitment of myeloid cells, proliferation, and cytokine secretion of M1 cells." (PMID 34671607, 2021). "Similar results were obtained for glomerulonephritis, IgG deposits in kidneys, and the activation status of innate and adaptive immune cells (expression of CD80 and CD69 on cDC2s and CD4+ T cells, respectively)." (PMID 34282144, 2021). "In patients with anti-MPO glomerulonephritis, MPO-specific CD4+ T cells mediate organ damage, recognizing MPO released by NETosis as an autoantigen, conducting delayed-type hypersensitivity promoting IFN-γ and IL-17A production." (PMID 33176801, 2020). "In an animal model of glomerulonephritis, it was evident that CD80 plays a detrimental role in kidney disease by promoting CD4+ survival and proliferation." (PMID 26063968, 2015). "By injecting agonistic CD137 monoclonal antibody (mAb), reduction in glomerulonephritis in MRL/lpr mice was demonstrated, besides reduction in CD4+ lymphocytes, anti-dsDNA production, germinal centre formation in secondary lymphoid organs, and mortality." (PMID 24000287, 2013). "CD4+ and CD8+ T cells were present in all patterns of glomerulonephritis except chronic glomerulonephritis." (PMID 20459816, 2010). "These include lack of injury in Mpo-/- mice or OVA immunised mice, a similar degree of injury in B cell deficient mice and the induction of glomerulonephritis by transfer of MPO-specific, but not OVA-specific CD4+ T cell clones." (PMID 29315316, 2018). "CD 4+ T cells predominate in proliferative patterns of glomerulonephritis, however the presence of CD4+ and CD8+ T cells were not different in intensity in different patterns of glomerulonephritis." (PMID 20459816, 2010). "Reduced CTLA-4 expression on circulating CD19+ B cells and CD4+ or CD8+ T cells in patients with primary proliferative and nonproliferative glomerulonephritis versus control participants was suggested to contribute to continuous activation of T cells and pathogenesis." (PMID 37345660, 2023).
endothelial dysfunction (38 papers, 2012 to 2025). In vascular diseases, endothelial dysfunction is a systemic pathological state of the endothelium (the inner lining of blood vessels) and can be broadly defined as an imbalance between vasodilating and vasoconstricting substances produced by (or acting on) the endothelium. "For example, Ho and colleagues found that nadir CD4 count of < 350 cells/μl was associated with endothelial dysfunction measured using flow mediated dilation (Beta coefficient of -1.22, 95% CI (-2.20 to -0.19)." (PMID 37161496, 2023). "In an outpatient HIV clinical study, CD4 count <500 cells/mm3 was found to be is an independent risk factor for incident CVD while in an independent HIV cohort endothelial dysfunction was associated with lower nadir CD4 count." (PMID 36831190, 2023). "Many studies in people living with HIV have shown an effect of low CD4 + T-cell count on MI risk, carotid atherosclerosis, arterial stiffness, and endothelial dysfunction." (PMID 35581554, 2022). "Markers of inflammation (IL-6, TNF-α, CRP), innate defense (cathelicidin), monocyte and macrophage activation (sCD14, sCD163 and, IL-2sRα), endothelial dysfunction (ET-1) and general immune health (CD4/CD8 ratio) were associated with lung abnormalities in HIV." (PMID 31830103, 2019). "HAART has been strongly associated with restoration of CD4 cell count and reduction of viral load, endothelial dysfunction, and abnormal coagulation activation." (PMID 29888267, 2018). "Compared to seronegative healthy controls, PLWH (both treatment-naïve individuals and those on ART) also showed higher plasma levels of asymmetric dimethylarginine (marker of endothelial dysfunction) associated with viral load, sCD14, D-dimer, and low CD4 counts." (PMID 38667287, 2024). "Clinical and experimental studies indicate that increased oxidative stress in HIV infection, sometimes exacerbated by some antiretroviral drugs, is associated with a reduction in CD4+ T-cell level, cytotoxicity, and endothelial dysfunction, contributing to atherosclerotic changes." (PMID 37627941, 2023). "Furthermore, CD4 + CD28− T cells were reported to be associated with endothelial dysfunction and arterial stiffness, which play a major role in the development of LN." (PMID 36320075, 2022). "In a separate study, adoptive transfer of Tregs (CD4+CD25+) prevented the increase in systolic BP and endothelial dysfunction in response to angiotensin II treatment compared with mice receiving effector T cells (CD4+CD25-)." (PMID 40341472, 2025). "It has been reported that the activation and migration of immune cells, including CD4+ T cells, B cells, and regulatory T cells, in PE patients contribute to endothelial dysfunction and placental inflammation, promoting pathological progression." (PMID 41409330, 2025). "Similar to what we observed for PD-1, the frequencies of CD4+/CD8+ T-cells expressing these inhibitory receptors correlate positively with endothelial dysfunction and severity-related plasma markers (syndecan-1, VCAM-1, and ferritin)." (PMID 40595657, 2025). "Pro-inflammatory T cell–derived cytokines such as IFN-γ and TNF-α (from CD8+ and CD4+Th1) and IL-17A (from the γδ-T cell and CD4+Th17) exacerbate hypertensive responses mediating both endothelial dysfunction and cardiac, renal, and neurodegenerative injury." (PMID 31321561, 2019). "Unlike other studies that have shown that low CD4 count is associated with endothelial dysfunction, our study reported the contrary." (PMID 37161496, 2023). "a CD4+ nadir < 350 cells/mm3 with endothelial dysfunction; c." (PMID 37627941, 2023). "Despite a straightforward effect in vitro, the actual contribution of CD4+ T cell-derived exosomes to endothelial dysfunction in vivo remains unclear." (PMID 36211827, 2022).
endothelial dysfunction (continued). "Pro-inflammatory T cell-derived cytokines, such as IFN-γ and TNF-α (from CD8+ and CD4 + Th1) and IL-17A (from the γδ-T cell and CD4 + Th17), were found to exacerbate hypertensive responses mediating both endothelial dysfunction and cardiac, renal, and neurodegenerative injury." (PMID 34359936, 2021). "Furthermore, the pro-inflammatory mediators secreted by aged immune cells can further ensue endothelial dysfunction and immune cell infiltration and promote pro-atherogenic immune cell responses, which is in line with the observed elevation of T-bet+ and RORγT+ CD4+ T cells in the aorta." (PMID 40603813, 2025). "Conversely, these endothelial dysfunction-related markers correlated negatively with the frequency of Ki-67+GzmB+ and Ki-67+CLA+ CD4+ T-cells." (PMID 40595657, 2025). "Plasma levels of the markers of endothelial dysfunction angiopoietin-2, syndecan-1, and Vascular cell adhesion molecule 1 (VCAM-1) show a moderate positive correlation with PD-1 expression in CD4+ T-cells (shown for TP2)." (PMID 40595657, 2025). "During atherogenesis, endothelial dysfunction elevates local CCL20 levels, directing CCR6 cells (B cells, immature dendritic cells, innate lymphoid cells (ILCs), regulatory CD4 T cells, and Th17 cells) to the subendothelial space." (PMID 39335632, 2024). "Our results point to exosomes as a novel class of bioactive factors secreted by CD4+ T cells in immune response and represent potential important triggers of NOX4-dependent endothelial dysfunction." (PMID 36211827, 2022). "Endothelial dysfunction in CD4-IL-17Aind/+ mice was not accompanied by a change in cardiac function or an increase in blood pressure." (PMID 31396305, 2019). "Recent data support the notion that HIV infection itself rather than antiretroviral therapy induces endothelial dysfunction with both micro- and macrovascular abnormalities correlating with CD4 counts in various studies." (PMID 25821605, 2015). "However, studies discussing the topics of CD4 count, viral load, and endothelial dysfunction are not unambiguous." (PMID 35336985, 2022). "In addition, neither CD4- and CD19-specific CD40 deficiency (accounting for T cells and B cells) nor GPb1a-specific CD40L deficiency (accounting for platelets) showed improvement in blood pressure or endothelial dysfunction." (PMID 39899926, 2025). "Others claim that neither CD4 count, nor HIV viral load, are the predictors of endothelial dysfunction." (PMID 35336985, 2022). "CD4+ and CD8+ cells were similar in patients with and without endothelial dysfunction." (PMID 38667287, 2024).
rectal cancer (38 papers, 2011 to 2025). A primary or metastatic malignant neoplasm that affects the rectum. "In rectal cancer tissues before radiotherapy, higher densities of CD4+ TIL, CD8+ TIL, and CD56+ TIL were associated with a greater proportion of patients achieving TRG0, TRG1, and TRG2 grades, while fewer patients exhibited TRG3." (PMID 40936903, 2025). "This novel finding argues a critical function of naïve CD3+CD4+ cells in the balance of advantageous antitumour immunity versus adverse systemic inflammation and thus, for the outcome of high-risk rectal cancer." (PMID 34961902, 2022). "This study validates the positive impact of nCRT combined with immunotherapy on the immune microenvironment of rectal cancer, particularly through increased infiltration of CD4+, CD8+ T cells, and CD56+ NK cells, which enhances the antitumor immune response." (PMID 40936903, 2025). "The MR analysis in this study suggests that CD4+ T cells serve as a protective factor against rectum cancer." (PMID 38533503, 2024). "KLF3 and KLF6 expressions were favourably related to the infiltration levels of all immune cell types except CD4+ T cells in rectal cancer." (PMID 35345512, 2022). "This was consistent with the favorable prognostics of a higher level of CD4+ T cells and CD4+/CD8+ T cell ratio infiltrated into the rectal cancer tissue." (PMID 35534879, 2022). "We conducted this study to test the association between the distribution and density of CD4+ and CD8+ T-cells in rectal-cancer tissue with tumor response to neoadjuvant therapy." (PMID 33442477, 2020). "After a BCAA enriched solution was infused into patients with rectal cancer, their immune status was improved with increased CD4+, CD4+/CD8+ and IL-2R." (PMID 28127425, 2017). "Interestingly, a higher CD4+/CD8+ ratio (i.e., a higher CD4+ cell count) in peripheral blood had a beneficial effect on the effectiveness of therapy, including radiation therapy in patients with rectal cancer." (PMID 41228297, 2025). "Whether the response of rectal cancer to nCRT is associated with the somatic mutations of KRAS or APC and infiltration of activated CD4+ T cells, NK cells, dendritic cells, or M2 macrophages should be verified in future investigations." (PMID 36621808, 2023). "CD4 over CD8 ratio is still a favorable factor for the rectal cancer prognosis." (PMID 35534879, 2022). "Effect of chemotherapy on the immune infiltrate was described in nonmetastatic rectal cancer, with an increased stromal CD8high and CD4 T cells after chemoradiotherapy, associated with a better prognosis." (PMID 34954864, 2022). "However, CBX8 expression was is closely tied to only with the infiltration of B cells and CD4+ T cells in rectal cancer." (PMID 33014884, 2020). "Also, in patients with rectal cancer, infusing a solution enriched in Leu, Ile and Val led to an increase in the number of CD4+ (Th) cells in blood, and led to an increased ratio of CD4+/CD8+ (cytotoxic T) cells in the blood." (PMID 31057483, 2019). "The results indicate that CD4/CD8 ratio may be a marker for rectal cancer prognosis." (PMID 35534879, 2022). "However, the association between the proportion of CD4+ T cells and both outcomes was not statistically significant among patients with rectal cancer." (PMID 34204621, 2021). "Rectal cancer patients showed a positive correlation between SIRT1 and CD4+ T cells (r = 0.319), CD8+ T cells (r = 0.109), macrophages (r = 0.509), and neutrophils (r = 0.282)." (PMID 41020376, 2025). "Comparison of pre-radiotherapy CD4+ T, CD8+ T, and CD56+ TIL grading with local efficacy in rectal cancer." (PMID 40936903, 2025). "In our study, nCRT combined with PD-L1 inhibitor therapy significantly enhanced the infiltration of immune cells, particularly CD8+ T cells and CD4+ T cells, into the TME, thus improving the therapeutic response in rectal cancer patients." (PMID 40936903, 2025).